S100PBP (S100P binding protein)
Synonyms: S100PBPR; FLJ12903
Tractability: PROTAC: ubiquitination databases record sites on it.
Gene: Protein-coding gene on chromosome 1 (32,816,408 to 32,858,879, forward strand). Ensembl gene ENSG00000116497.
Subcellular location: Nucleus
Subcellular location (Human Protein Atlas): Nuclear speckles; Cytosol
Gene Ontology:
Molecular function: calcium-dependent protein binding; protein binding
Cellular component: nuclear speck; nucleus
Genetic constraint (gnomAD): Loss-of-function variants: 8 observed, 27.43 expected, observed/expected ratio (o/e) 0.29, 90% interval 0.17 to 0.53. The upper end of that interval is the gene's LOEUF score, 0.53, which puts it in group 2 of 6, group 1 being the genes least tolerant of losing a copy. Missense variants: 417 observed, 414.23 expected, observed/expected ratio (o/e) 1.01, 90% interval 0.93 to 1.09. Synonymous variants: 147 observed, 156.64 expected, observed/expected ratio (o/e) 0.94, 90% interval 0.82 to 1.08.
Homologues: Orthologues: chimpanzee S100PBP (99% identical), macaque S100PBP (95% identical), pig S100PBP (76% identical), rabbit S100PBP (71% identical), rat S100pbp (69% identical), guinea pig S100PBP (69% identical), mouse S100pbp (69% identical), dog S100PBP (60% identical), tropical clawed frog s100pbp (18% identical).
Diseases named in the same sentence as S100PBP in open-access papers:
S100PBP is named in the same sentence as 13 diseases in open-access papers, as found by Europe PMC text mining. Sharing a sentence is not in itself a finding about the gene and the disease. The quoted sentences say what the papers report.
pancreatic cancer (6 papers, 2014 to 2025). "The loss of S100PBP may result in the increased invasion of pancreatic cancer cell lines." (PMID 30453668, 2018). "S100PBP has been reported to inhibit the adhesion of pancreatic cancer cells through the S100PBP/CTSZ/RGD αvβ5 pathway and plays a tumor suppressor role." (PMID 40204913, 2025). "With 3D confocal images, we also observed dual-staining of these cells for combinations of macrophage markers (CD204 or CD206) and pancreatic cancer markers ZG16B or S100PBP." (PMID 28957348, 2017). "Lu et al29 found that S100PBP may inhibit pancreatic cancer cell adhesion through the LMNB1 and PRKRA gene pathways." (PMID 39128058, 2024). "Integrated bioinformatic analysis of our array data to identify genes and pathways downstream of S100PBP in pancreatic cancer showed its role in miRNA signalling, in cytoskeletal anchoring and protein binding activity, as well as its role in inhibiting migration and invasion." (PMID 37794133, 2023). "Moreover, it was recently demonstrated that, in adenocarcinoma of the pancreatic duct, S100P-binding protein inversely regulates Cat X expression – lower levels of S100P-binding protein increased Cat X, cell adhesion and metastatic potential of pancreatic cancer cells." (PMID 24725597, 2014). "Given that the high expression of S100P and low expression of S100PBP correlate with poor survival in PDAC patients, this study highlights the potential clinical relevance of S100PBP in pancreatic cancer." (PMID 37794133, 2023).
pancreatic ductal adenocarcinoma (5 papers, 2014 to 2024). An infiltrating adenocarcinoma that arises from the epithelial cells of the pancreas. "Lines et al28 reported that in pancreatic ductal adenocarcinoma and metastatic lesions, S100PBP expression is notably diminished and that the adhesion of tumor cells is markedly reduced after S100PBP upregulation and increased after S100PBP silencing." (PMID 39128058, 2024). "We have previously shown that expression of S100PBP, an S100P binding partner, gradually decreases during progression of pancreatic ductal adenocarcinomas (PDAC)." (PMID 37794133, 2023). "S100PBP level is suggested to be related to pancreatic ductal adenocarcinoma." (PMID 34712325, 2021).
breast carcinoma (4 papers, 2013 to 2021). "In breast cancer, S100PBP expression was markedly related to patient prognosis and different metastatic sites." (PMID 34712325, 2021). "S100PBP expression correlated with spread to different metastatic sites in breast cancer, although its precise molecular function is poorly understood." (PMID 32734521, 2020).
glioma (2 papers, 2021 to 2023). A benign or malignant brain and spinal cord tumor that arises from glial cells (astrocytes, oligodendrocytes, ependymal cells). "In our previous study, we developed an S100 family-based prognostic signature consisting of five genes of S100A11, S100A16, S100B, S100PBP and S100A13 for glioma patients." (PMID 37151881, 2023).
cervical cancer (1 paper, 2019). A primary or metastatic malignant neoplasm involving the cervix. "miR-944 was predicted to play an oncogenic role in cervical cancer malignancy by repressing these two genes (HECW2 and S100PBP) that function as a tumor suppressors." (PMID 31060525, 2019).
male infertility (1 paper, 2025). The inability of the male to effect fertilization of an ovum after a specified period of unprotected intercourse. "S100pbp-knockout mice exhibit male infertility and spermatogenesis arrest at meiotic metaphase I, resulting from a drastic reduction in XY crossovers." (PMID 40204913, 2025).
pancreatic adenocarcinoma (1 paper, 2023). "Finally, to establish the potential clinical relevance of S100P and S100PBP, we studied TCGA PanCancer Atlas dataset on 176 pancreatic adenocarcinoma patients and generated Kaplan–Meier survival plots." (PMID 37794133, 2023).
tumor (6 papers, 2019 to 2025). "Taken together, in the present study we demonstrate a novel tumour suppressive role of S100PBP via its regulation of cellular morphology, motility, invasion and pro-survival capabilities." (PMID 37794133, 2023). "In this study we report novel tumour suppressive functions of S100PBP, including modulation of cytoskeletal reorganisation, cell morphology, motility and invasion." (PMID 37794133, 2023). "Finally, analysis of TCGA PanCancer Atlas PDAC datasets demonstrated poor prognosis in patients with high S100P and low S100PBP expression, suggesting that S100PBP is a novel tumour suppressor gene with potential clinical utility." (PMID 37794133, 2023). "Finally, low RhoB expression in human PDAC samples, which mimics the behaviour of S100PBP described in our previous study, firmly implicates S100PBP in the same RhoB signalling circuitry and suggests its tumour suppressive functions." (PMID 37794133, 2023). "In this study, we therefore aimed to unravel the detailed roles of S100PBP, its interactions with effector molecules which may modulate cell morphology, motility and invasion, and cell survival, all of which could corroborate its potential role of novel tumour suppressor." (PMID 37794133, 2023).
bacterial infection (2 papers, 2021 to 2022). "We identified five genes—S100PBP, AKAP1, USP6NL, CDON and SULF2—in five different patient subgroups that have been associated with viral and/or bacterial infection in the literature." (PMID 36517845, 2022). "Setting a cut off of 4 for the fold change ratio of S100PBP allowed the best differential resolution, scoring bacterial infection in 5 of the 6 infected pigs, whereas only one healthy pig was scored as a false positive for bacterial infection." (PMID 34555028, 2021). "The combination of three genes, MxA (viral), IL-8 (bacterial) and S100PBP (bacterial) in a quota, turned out as a potential read-out for differentiation between viral and bacterial infections in pigs." (PMID 34555028, 2021). "From this selection three virally upregulated genes (IFI44L, MxA, RSAD2) were further evaluated together with four genes supposedly indicative of bacterial infections (IL-1β, IL-8, FAM89A, S100PBP) on clinical samples." (PMID 34555028, 2021).
cancer (2 papers, 2021 to 2023). A tumor composed of atypical neoplastic, often pleomorphic cells that invade other tissues. "HDAC inhibitors like vorinostat have shown promising outcomes by augmenting cell death and supressing advanced pancreatic (and other) cancers, and our data now implicate S100PBP in the mechanisms of their actions." (PMID 37794133, 2023). "S100PBP is differentially expressed in various organs and disease states, which is dependent on tissue and cancer type." (PMID 34712325, 2021).
S100PBP also shares sentences with these, for which no sentence is quoted: infection (1 paper); metastatic disease (1); viral infections (1).